AURKA (aurora kinase A)
Diseases named in the same sentence as AURKA in open-access papers (continued):
Sharing a sentence is not in itself a finding about the gene and the disease.
glioblastoma (38 papers, 2010 to 2025). The most malignant astrocytic tumor (WHO grade IV). "In glioblastoma, AURKA has been linked to the tumor cells’ capacity of unlimited proliferation, maintenance of cellular stemness, and microinvasion." (PMID 33673490, 2021). "Results strongly suggested that increased AURKA mRNA level in glioblastoma is caused by AURKA copy number aberrant amplification." (PMID 31706255, 2019). "This is somewhat surprising because AURKA is a proliferation marker, but females with glioblastomas generally have better outcomes than their male counterparts." (PMID 41024254, 2025). "Aurora-A kinase (AURKA) is a Ser/Thr protein kinase involved in cell division that contributes to the proliferation and growth of solid tumors, including glioblastoma." (PMID 38534215, 2024). "AURKA inhibition has been reported to induce changes in various pathways within tumors, and it can even trigger metabolic reprogramming in glioblastoma." (PMID 38521813, 2024). "Next, JQ1-sensitive and resistant glioblastoma cells displayed a synergistic effect when JQI was combined with an AURKA inhibitor." (PMID 38183103, 2024). "POLE2 promotes the malignant phenotype of glioblastoma by promoting AURKA-mediated stabilization of FOXM1." (PMID 37880682, 2023). "AURKA is a key factor in the pathogenesis of glioblastoma, and increased levels of ATP5F1A and ATP5F1B were observed in glioblastoma models and are accompanied by an upregulation of oxidative metabolism." (PMID 37386025, 2023). "Aurora kinase A (AURKA) has emerged as a drug target for glioblastoma for being highly involved in cell proliferation, migration, and invasion." (PMID 35832194, 2022). "As AURKA inhibitors have demonstrated anti-tumor activities either as a single agent or in combination in MYCN-positive human glioblastoma and AURKs are attractive therapeutic targets in c-Myc-driven lymphoproliferative disorders." (PMID 34359608, 2021). "To extent these findings related to MYC phosphorylation/degradation further in the context of glioblastoma cells, we have generated a kinase-dead mutant of Aurora kinase A (D274N)." (PMID 34471141, 2021). "In this study, we investigated how Aurora kinase A inhibition affects glioblastoma cell metabolism and how the derived knowledge from these studies can be leveraged for the design of drug combination therapies." (PMID 34471141, 2021). "Several members have been described and Aurora kinase A has been identified as a target for glioblastoma therapy, especially because specific inhibitors exist (alisertib, MLN8237) that have shown limited single-agent efficacy in orthotopic GBM model systems." (PMID 34471141, 2021). "Here, the authors show that AURKA inhibition induces metabolic reprogramming, which leads to increased mitochondrial activity and inhibition of oxidative metabolism sensitizes glioblastoma cells to AURKA inhibition." (PMID 34471141, 2021). "Specific AURKA inhibitors have been reported to induce a G2/M phase arrest in glioblastoma cells culminating in increased percentage of apoptotic cells." (PMID 33673490, 2021). "VX680 (tozasertib), a pan aurora kinase inhibitor, and MLN8237 (alisertib), a highly selective AURKA inhibitor, have been found to effectively suppress cell proliferation and prolong the survival of mice with intracranial glioblastoma xenografts." (PMID 28595628, 2017). "Conversely, the transcriptional activity of the AURKA promoter has been shown to increase following the interaction with the ΔEGFR/STAT5 complex in glioblastoma cells." (PMID 25097550, 2014). "The expression of AURKA has been reported to be higher in females with glioblastoma." (PMID 41024254, 2025). "Interestingly, GSK3β regulates c-Myc itself, and our previous research has connected AURKA activity to c-Myc levels in a GSK3β-dependent manner in model systems of glioblastoma, involving both adult and pediatric model systems." (PMID 38995006, 2024).
glioblastoma (continued). "Examining these relationships in greater depth will provide valuable insights that could guide the development of more effective combination treatment strategies targeting both the AURKA kinase and the immune checkpoint axis for glioblastoma patients." (PMID 38995006, 2024). "AURKA has been consistently established as a therapeutic target for glioblastoma." (PMID 38534215, 2024). "Although direct evidence of how miR-124-3p regulates AURKA remains unknown in HCC, existing literature supports the targeting of AURKA in bladder cancer and glioblastoma." (PMID 39598228, 2024). "Aurora kinase A (AURKA) which is involved in the regulation of cell division and has been linked to glioblastoma proliferation capacity and therapy resistance, was among the most significant differentially expressed genes and showed a downregulation upon combination treatment." (PMID 33673490, 2021). "AURKA inhibitor synergizes with BET inhibitor against MYCN-positive human glioblastoma." (PMID 34359608, 2021). "Glioblastoma patients are treated with Aurora kinase A (AURKA) inhibitors but resistance can occur." (PMID 34471141, 2021). "Also, aurora kinase A inhibitors have demonstrated glycolysis suppression in glioblastoma." (PMID 38794139, 2024). "For example, a recent study reported a synergistic relationship between inhibitors of Aurora Kinase A (AURKA) and BET proteins in MYC-driven glioblastoma cells." (PMID 38183103, 2024). "Next, we determined the impact of Aurora kinase A on key glycolytic transporters (SLC2A1) and enzymes (HK2, LDHA), some of which are upregulated in glioblastoma as compared to normal brain tissue." (PMID 34471141, 2021). "Aurora kinase A (AURKA) has emerged as a drug target for glioblastoma (GBM)." (PMID 34471141, 2021). "Several studies have suggested that combining the AURKA inhibitor alisertib with the FAO inhibitor etomoxir reduces glioblastoma cell growth, enhances glioblastoma cell death, and extends overall survival in orthotopic glioblastoma patient-derived xenograft models." (PMID 40097417, 2025). "Furthermore, AURKA blockade improves the cytotoxic effects of TMZ and ionizing radiation on glioblastoma cells and xenograft models." (PMID 38534215, 2024). "Furthermore, PPI network analysis demonstrated that AURKA and KDR genes were hub driver genes of glioblastoma." (PMID 31706255, 2019). "PIK3CG, SRC, AURKA, CDK7, and PLAT might be key molecular targets of plinabulin in glioblastoma." (PMID 39877641, 2025).
liver cancer (30 papers, 2015 to 2026). An epithelial or non-epithelial malignant neoplasm that arises from the liver. "The gene signature based on AURKA successfully classified patients with liver cancer into high-, moderate- and low-risk groups." (PMID 34917126, 2021). "Furthermore, survival analysis indicated that the expression levels of CYP1A2, ESR1, and AURKA are significantly associated with the prognosis of liver cancer patients, providing potential biomarkers for clinical treatment." (PMID 40864066, 2025). "AURKA lle31Phe enhanced the predisposition of HBV-infected individuals to develop liver cancer." (PMID 37393234, 2023). "We hypothesize that the AURKA(V352I) mutation plays a role in liver cancer formation and drug responsiveness." (PMID 31269749, 2019). "Silencing AURKA prevents liver cancer cells from becoming invasive, whereas overexpressing AURKA induces epithelial‐mesenchymal transition." (PMID 39764737, 2025). "This indirect regulation was observed in a liver cancer cell line (MHCC‐97H) supporting the role of the ID1/AURKA/MYC axis in promoting a highly malignant phenotype with enhanced metastatic ability and drug resistance." (PMID 38590119, 2024). "Cinobufagin is known to have an anti-tumor effect in liver cancer cells by inhibiting the aurora kinase A—mechanistic target of rapamycin—eukaryotic initiation factor 4E axis." (PMID 37819146, 2023). "The oncogene Aurora kinase A (AURKA) is involved in a variety of tumors; however, its role in liver cancer is poorly understood." (PMID 34917126, 2021). "In liver cancer cell lines, overexpression of AURKA can reduce PTEN and increase the phosphorylation of Akt and mTOR to induce cell proliferation and transformation." (PMID 31269749, 2019). "In this study, we aim to explore the function of wild-type and mutant AURKA in liver cancer formation." (PMID 31269749, 2019). "Importantly, TCHP inhibition not only suppresses tumor growth directly but also sensitizes liver cancer cells to the AURKA inhibitor alisertib, allowing tumor suppression at reduced drug doses and mitigating toxicity risks." (PMID 42034602, 2026). "Therefore, the expression levels of AURKA, BIRC5, CCNB1, CDK1, CDKN3 and TYMS served as diagnostic markers for liver cancer patients." (PMID 37393234, 2023). "AURKA’s specific inhibitor alisertib exerts effective therapeutic effect on liver cancer with low TIALD expression, which might provide a new insight into HCC therapy." (PMID 37773181, 2023). "Moreover, the combination of KRIBB11 and an Aurora Kinase A (AURKA) inhibitor (danusertib) showed excellent anti-tumor effects on liver cancer in vitro and in vivo." (PMID 37153737, 2023). "The analysis showed that the AURKA gene was upregulated (log2 fold change >1.5 and adjusted p-value <0.05), which indicated that the mRNA expression levels of AURKA differ significantly between normal liver tissue and liver cancer tissue." (PMID 34917126, 2021). "In addition to CCNB1, CDK1, CDC45, BUB1B, and CCNA2, we also identified five hub genes in Chinese liver cancer, namely AURKA, KIF11, TOP2A, TPX2, and HMMR, which play a crucial role in regulating the cell cycle." (PMID 34257537, 2021). "Investigations showed that AURKA played an important role in liver cancer progression." (PMID 34917126, 2021). "For instance, previous studies showed that Polymorphism rs1047972 in the AURKA gene raises the level of liver cancer risk in spite of not having significant relation with bladder cancer risk." (PMID 34337875, 2021). "Aurora kinase A forms a protein complex with c-Myc in liver cancer." (PMID 30197758, 2018). "Besides, AURKA also involved in formation of secondary liver cancer." (PMID 35078445, 2022).
liver cancer (continued). "Meanwhile, immunohistochemical results of AURKA, CCNB1, CDC20 and TOP2A were found through the HPA database, which also confirmed that there were significant differences between liver cancer tissues and normal adjacent tissues." (PMID 39537209, 2024). "Inhibition of aurora kinase A (AURKA) can suppress ferroptosis in upper gastrointestinal cancers, and RRM2 protects against ferroptosis in liver cancer." (PMID 34395526, 2021). "In addition, the combined effects of CDK1 and other cell cycle-related proteins, such as aurora kinase A (AURKA), are also considered as an important target for the treatment of liver cancer." (PMID 40332418, 2025). "The specific mechanisms of AURKA and related genes in liver cancer have not been thoroughly investigated." (PMID 34917126, 2021). "Currently, the immunological value of AURKA in liver cancer has not been reported." (PMID 34917126, 2021). "Thus far, no study investigated the role of AURKA gene and AURKA-related prognostic genes in liver cancer." (PMID 34917126, 2021). "Despite the limited evidence about the possible role of AURKA in regulating miRNAs in HCC, other cancers may suggest the existence of new AURKA-miRNA regulatory axes not yet explored in liver cancers." (PMID 39598228, 2024).
bladder cancer (28 papers, 2007 to 2026). "For example, AURKA promotes tumor proliferation and was associated with worse prognosis in bladder cancer and gastrointestinal cancer 41-42." (PMID 33029085, 2020). "In bladder cancer, AURKA/STK15, the gene encoding Aurora-A at locus 20q13.2 is commonly amplified and the resulting overexpression is correlated with critical clinical parameters such as invasion, metastasis and poor survival." (PMID 17326833, 2007). "Mechanistically, this relationship was attributed to the transcriptional regulation of aurora kinase A (AURKA) by PUF60 on bladder cancer cell behavior." (PMID 39132499, 2024). "In contrast to silencing individual genes, co-silencing in STIL and AURKA produces more encouraging results in bladder cancer cells." (PMID 37101292, 2023). "Another study in bladder cancer demonstrated that active cathepsin B activated the AURKA/PI3K/AKT axis and promoted angiogenesis." (PMID 36973424, 2023). "In human bladder cancer cells, curcumin down-regulates the promoter activity of AURKA, thus inhibiting AURKA at the transcriptional level." (PMID 35699421, 2022). "Related studies have also shown high levels of AURKA as an indicator of poor prognosis in bladder cancer." (PMID 36685952, 2022). "The biological roles of LINC00958, miR-490-3p, and AURKA in bladder cancer cells were analyzed using CCK8, BrdU, and transwell assays." (PMID 34702201, 2021). "Collectively, miR-490-3p suppressed bladder cancer cell proliferation and invasion, while boosting cell apoptosis by targeting AURKA." (PMID 34702201, 2021). "Taken together, our findings indicate that LINC00958 aggravates cell growth and invasion, but hampers apoptosis of bladder cancer cells via the miR-490-3p/AURKA axis." (PMID 34702201, 2021). "As a nucleic acid-binding protein, PUF60 contributes to malignant phenotypes of bladder cancer through binding to AURKA promoter and activating AURKA transcription." (PMID 33451333, 2021). "Our study revealed that LINC00958 facilitated cell proliferation and invasion, and suppressed cell apoptosis by sponging miR-490-3p and upregulating AURKA, thus inspiring a new treatment method for bladder cancer." (PMID 34702201, 2021). "Meanwhile, the role of the LINC00958/miR-490-3p/AURKA axis in bladder cancer also needs to be proven both in vivo and clinically." (PMID 34702201, 2021). "AURKA has also been reported to be a significant facilitator in bladder cancer and has been studied in miRNA-mRNA interaction networks." (PMID 34702201, 2021). "In this study, we sought to determine the role of the LINC00958-miR-490-3p-AURKA axis in bladder cancer." (PMID 34702201, 2021). "For example, overexpression of AURKA accelerated cell proliferation and reduced cell apoptosis, and high AURKA expression predicted poor prognosis in bladder cancer." (PMID 34702201, 2021). "Our study confirmed that the expression of LINC00958 and AURKA was upregulated in bladder cancer, while the expression of miR-490-3p was downregulated." (PMID 34702201, 2021). "To corroborate that PUF60 indeed regulated bladder cancer cell growth by mediating AURKA expression, we conducted the expression rescue experiments." (PMID 33117697, 2020). "Overexpression of PUF60 significantly promoted cell viability and colony formation in bladder cancer cells, while treatment with AURKA specific inhibitor reversed this promotive effect." (PMID 33117697, 2020). "PUF60 knockdown significantly inhibited cell viability and colony formation capacity in bladder cancer cells, whereas AURKA overexpression reversed this inhibition effect." (PMID 33117697, 2020). "In our future study, we will perform animal experiments to verify the oncogenic role of PUF60/AURKA in bladder cancer in vivo." (PMID 33117697, 2020). "AURKA (aurora kinase A) was shown to promote cell proliferation and predicts poor prognosis in bladder cancer." (PMID 31781484, 2019).
bladder cancer (continued). "In this study, we performed sequential gene expression profiling (GEP) from patients of primary bladder cancer (PBC) or undergoing radical cystectomy (RC) to reveal the relationship between AURKA expression, clinical characteristics and overall survival." (PMID 30547784, 2018). "With these criteria, the AURKA FISH test was positive for samples from 185 patients with bladder cancer." (PMID 28102366, 2017). "Our FISH test for AURKA copy number in exfoliated urothelial cells from voided urine sediments detected bladder cancer with a high degree of specificity and sensitivity." (PMID 28102366, 2017). "This feature together with the expression signature of AURKA downstream regulatory targets was enriched in a highly aggressive basal intrinsic subtype of bladder cancer." (PMID 28102366, 2017). "The ubiquitous involvement of AURKA in bladder cancer made it suitable to be an effective biomarker for its detection." (PMID 28102366, 2017). "Here we show that AURKA, a protein kinase best known for its role in promoting mitotic spindle assembly and mitosis, is overexpressed in basal bladder cancers and controls invasion in preclinical bladder cancer models." (PMID 28102366, 2017). "The overexpression of AURKA combined with the expression signature of AURKA downstream regulatory genes was enriched in the basal intrinsic molecular subtype of bladder cancer which exhibited highly aggressive clinical behavior." (PMID 28102366, 2017). "The fact that AURKA and its downstream effects are highly enriched in basal cancers provides additional clues to the pathogenesis of this highly aggressive subtype of bladder cancer." (PMID 28102366, 2017). "Less than 20% abnormal cells with more than 2 AURKA gene copies were detected in samples from the remaining 47 patients with bladder cancer." (PMID 28102366, 2017). "We used RNA interference to examine the effects of AURKA overexpression in human bladder cancer cells." (PMID 28102366, 2017). "In summary, our study has identified a novel mechanism for AURKA regulating cell invasion and contributing to aggressive clinical behavior of bladder cancer and has established a role for AURKA as a detection marker for the disease." (PMID 28102366, 2017). "The levels of AURKA were significantly higher in bladder cancer compare to normal tissues." (PMID 38612711, 2024). "Silencing AURKA inhibits cell proliferation in the bladder cancer cell lines." (PMID 38612711, 2024). "In bladder cancer cells, AURKA expression was affected by STIL." (PMID 37101292, 2023). "In bladder cancer, we found that the expression of AURKA is up-regulated." (PMID 37101292, 2023). "Another study indicated that AURKA targeted by miR-124-3p could enhance proliferation and migration and impair apoptosis of bladder cancer cells." (PMID 34702201, 2021). "Upregulation of AURKA has been reported in bladder cancer progression, which might be a potential therapeutic target for bladder cancer." (PMID 34702201, 2021). "Furthermore, LINC00958 enhanced cell growth and invasion, but suppressed apoptosis of bladder cancer cells by inhibiting miR-490-3p and upregulating AURKA expression." (PMID 34702201, 2021). "Moreover, LINC00958 sponges miR-490-3p to upregulate AURKA expression, thereby promoting carcinogenesis in bladder cancer cells." (PMID 34702201, 2021). "We further confirmed the biological action of miR-490-3p on AURKA in bladder cancer." (PMID 34702201, 2021). "Finally, we further elucidated that LINC00958 facilitated bladder cancer progression via the miR-490-3p/AURKA axis." (PMID 34702201, 2021). "Furthermore, miRNA-124-3p inhibited cell proliferation and migration, but enhanced cell apoptosis by reducing AURKA in bladder cancer." (PMID 34702201, 2021). "In addition, miR-490-3p levels were enhanced by 3-fold in the tumor tissues compared to the normal tissues, and were negatively correlated with AURKA in bladder cancer tissues." (PMID 34702201, 2021).